TYSND1 (trypsin like peroxisomal matrix peptidase 1)
Description:
Peroxisomal protease that mediates both the removal of the leader peptide from proteins containing a PTS2 target sequence and processes several PTS1-containing proteins. Catalyzes the processing of PTS1-proteins involved in the peroxisomal beta-oxidation of fatty acids.
Synonyms: MGC34695; NET41
Tractability: PROTAC: ubiquitination databases record sites on it; its protein half-life has been measured.
Gene: Protein-coding gene on chromosome 10 (70,137,981 to 70,146,700, reverse strand). Ensembl gene ENSG00000156521.
Subcellular location: Peroxisome
Subcellular location (Human Protein Atlas): Centrosome; Nucleoplasm; Cytosol
Pathways (Reactome):
Protein localization: Peroxisomal protein import; TYSND1 cleaves peroxisomal proteins
Gene Ontology:
Molecular function: protease binding; protein binding; serine-type endopeptidase activity
Biological process: protein processing; proteolysis; regulation of fatty acid beta-oxidation
Cellular component: membrane; peroxisome; cytosol; peroxisomal matrix
Genetic constraint (gnomAD): Loss-of-function variants: 30 observed, 28.6 expected, observed/expected ratio (o/e) 1.05, 90% interval 0.78 to 1.42. The synonymous counts are far from expectation, so gnomAD's model fits this gene poorly and the ratio says little. Missense variants: 785 observed, 646.7 expected, observed/expected ratio (o/e) 1.21, 90% interval 1.14 to 1.29. Synonymous variants: 352 observed, 292.3 expected, observed/expected ratio (o/e) 1.2, 90% interval 1.1 to 1.32.
Homologues: Orthologues: chimpanzee TYSND1 (98% identical), macaque TYSND1 (96% identical), dog TYSND1 (82% identical), guinea pig TYSND1 (81% identical), rat Tysnd1 (80% identical), mouse Tysnd1 (80% identical), pig TYSND1 (79% identical), zebrafish tysnd1 (38% identical), tropical clawed frog tysnd1 (36% identical), Drosophila melanogaster CG3589 (22% identical).
Diseases named in the same sentence as TYSND1 in open-access papers:
TYSND1 is named in the same sentence as 6 diseases in open-access papers, as found by Europe PMC text mining. Sharing a sentence is not in itself a finding about the gene and the disease. The quoted sentences say what the papers report.
Ataxia (1 paper, 2013). Ataxia refers to impaired coordination of voluntary muscle movement. "Although Tysnd1−/− mice received twice the amount of phytol as the Phyh−/− mice we did not observe ataxia, indicating only a mild impairment of phytanic acid metabolism in Tysnd1−/− mice." (PMID 23459139, 2013).
breast carcinoma (1 paper, 2022). "Many of those hits were supported by literature, whereby some hits were so far overlooked in the context of breast cancer (e.g., Lonp1, Uspl1) or cancer in general (e.g., Psmd13, Tysnd1)." (PMID 36313646, 2022).
male infertility (1 paper, 2013). The inability of the male to effect fertilization of an ovum after a specified period of unprotected intercourse. "It is therefore possible that TYSND1 deficiency in human might cause phenotypes that are clinically diagnosed as a mild RCDP1 variant accompanied by male infertility." (PMID 23459139, 2013). "Male infertility is one of the major phenotypic manifestations of Tysnd1 deficiency." (PMID 23459139, 2013).
peroxisomal disease (1 paper, 2013). A group of congenital disorders of lipid metabolism, caused by loss of the normal peroxisomes. "Since Tysnd1 acts as a protease that affects the function of its substrates in the mouse model, we anticipate a new human peroxisomal disease entity caused by impaired TSYND1 functions that trigger a combination of mild dysfunctions among TYSND1 processing-dependent peroxisomal enzymes." (PMID 23459139, 2013).
Zellweger syndrome (1 paper, 2013). "Loss of Tysnd1 interferes with the peroxisomal localization of Acaa1, Phyh, and Agps, which might cause the mild Zellweger syndrome spectrum-resembling phenotypes." (PMID 23459139, 2013).
cancer (1 paper, 2022). A tumor composed of atypical neoplastic, often pleomorphic cells that invade other tissues. "Other depletion hits, such as Psmd13 and the “peroxisomal matrix protein trypsin domain-containing 1” (Tysnd1), have to our knowledge not been postulated to be important for cancer growth." (PMID 36313646, 2022).